TNF (tumor necrosis factor)
Diseases named in the same sentence as TNF in open-access papers (continued):
Sharing a sentence is not in itself a finding about the gene and the disease.
depression (continued). "Although these studies indicate little relationship, the pathophysiology of TNFα effecting cognition and mood suggests that a relationship may be found especially in populations where both depression and inflammatory diseases are prevalent, such as found for Mexican-Americans." (PMID 28629481, 2017). "Intense cardiovascular exercise has been shown to elicit generalized fatigue and depression associated with changes in the expression of neurotransmitters such as glutamine, dopamine and 5-HTP and the production of large quantities of proinflammatory cytokines such as IL-1β, IL-6 and TNF- α." (PMID 28360847, 2017). "Thus the significantly low level of serum vitamin D in AD patients with depression may have contributed to the raised level of circulating IL 6 and TNF α in such patients." (PMID 28580183, 2017). "The monocyte-T-lymphocyte theory of depression, devised by Smith and Maes in the early 1990s, proposes that increased proinflammatory cytokine secretion in the form of IL-1β, TNF-α, and IFN-γ is responsible for the initiation and maintenance of a depressive episode." (PMID 26775294, 2016). "Excess levels of TNF-α may play a pivotal role in the pathophysiology of depression." (PMID 27187381, 2016). "In addition, the relation between TNF-α and depression in SLE patients may be explained by the long-term use of corticosteroids." (PMID 26732584, 2016). "Therefore, we integrate recent progress of the relationship between TNF-α and depressive disorders." (PMID 27187381, 2016). "Additionally, intracerebroventricularly injected TNFα was shown to induce depression-like symptoms." (PMID 25698933, 2015). "The majority of major depressive patients included in our meta-analysis could be classified as severely or very severely depressed; IL-6, CRP and TNF-α were more strongly associated with severe than non-severe forms of depression." (PMID 26065825, 2015). "Thus, we next analyzed the expression levels of the genes encoding for three of the most relevant pro-inflammatory cytokines, IFN-γ, IL-1β, and TNF, for the anti-inflammatory cytokine IL-10 and for the enzyme iNOS, all previously addressed in studies on the etiology of depression." (PMID 26696854, 2015). "Thus, stress via enhanced release of pro-inflammatory cytokines such as TNF-α, IL-1β and IL-6 may not only precipitate depression, but may also accelerate the neurodegenerative processes." (PMID 25514226, 2014). "However, once elevated in the setting of depression, TNF-α, by reducing endothelial nitric-oxide synthase (eNOS) expression, can lead to neuronal and vascular injury through a decrease in nitric oxide bioavailability and the formation of reactive oxygen species." (PMID 22216404, 2011). "Disease symptoms include lethargy, depression, failure to concentrate, anorexia, sleep disturbances, reduction in personal hygiene or social withdrawal, and are mediated by proinflammatory cytokines, such as interleukin-1 (IL-1), interleukin-6 (IL-6) and tumor necrosis factor α (TNFα)." (PMID 21831269, 2011). "TNF-α might, for example, contribute to the pathogenesis of depression by an activation of the hypothalamo-pituitary-adrenocortical (HPA) axis, an activation of neuronal serotonin transporters and the stimulation of the indoleamine 2,3-dioxygenase which leads to tryptophan depletion." (PMID 19506720, 2008). "LLE improved CRS-induced anxiety- and depression-like behaviors, reduced microglial activation in the hippocampus, and suppressed TLR4/MyD88/NF-κB signaling and downstream cytokine release (TNF-α, IL-6, IL-1β)." (PMID 42255668, 2026). "Elevated pro-inflammatory cytokines, including tumor necrosis factor-α (TNF-α), interleukin-1β (IL-1β), and interleukin-6 (IL-6), have been observed in both patients and animal models of depression." (PMID 41535967, 2026).
depression (continued). "The aim of the paper was to analyze the relationship between somatization in elderly patients with major depressive disorder (MDD) and brain-derived neurotrophic factor (BDNF), IL-6, IL-10, and TNF-a cognitive function, and sleep quality (SQ)." (PMID 40821647, 2025). "IL‐18, TNF‐α, and the proinflammatory PC1 values positively correlated with AUD severity and anxiety/depression measures." (PMID 40317574, 2025). "Inflammatory biomarkers such as C-reactive protein (CRP), interleukin-6 (IL-6), and tumor necrosis factor-alpha (TNF-α) are elevated in both periodontitis and depression, raising the possibility of a shared inflammatory pathway." (PMID 40656387, 2025). "Clinical and research data have reported that inflammatory markers in both the blood and the brain, including interleukin IL-1β, IL-6, and tumor necrosis factor TNF-α, are markedly elevated in individuals with major depression." (PMID 40006068, 2025). "Another meta-analysis reported that individuals with depression exhibited notably elevated blood levels of CRP, IL-6, and TNF-α relative to healthy controls, with effect sizes ranging from moderate to large (0.54 to 1.97)." (PMID 40363978, 2025). "The level of interleukin (IL)-1β, IL-6, tumor necrosis factor α (TNF-α), and depression-like behavior in rats showed that the CP/CPPS complicated with depression model was established successfully." (PMID 40576719, 2025). "Several meta-analyses have consistently demonstrated elevated levels of proinflammatory markers, including IL-6, TNF-α, and CRP, in subsets of patients with depression." (PMID 41155383, 2025). "NLRP3 inflammasome, microglia, TNF-α, and brain-derived neurotrophic factor (BDNF) were the basis of neuroinflammation in depression." (PMID 40520890, 2025). "C3, which shows a positive correlation with TNF-α, IL-6, and IL-1β, can suppress inflammation in the context of CSVD with depression." (PMID 40584618, 2025). "Growing evidence indicates brain inflammation in depression in the form of heightened translocator protein (TSPO) expression, and increased IL-6 and TNF-α in the cerebrospinal fluid (CSF)." (PMID 39959848, 2025). "Meta-analysis showed that TNF-α was lower in the test group compared with the control group (SMD: −2.09, 95% CI: −2.83, −1.34), indicating that depression animals treated with acupuncture had significantly lower levels of TNF-α (P<0.05)." (PMID 41244868, 2025). "Patients with depression exhibit elevated levels of pro-inflammatory cytokines (IL-6, IL-8), interferon-gamma (IFN-γ), and TNF-α." (PMID 40699781, 2025). "Thus, during HIV infection, elevated TNF-α levels disrupts the integrity of the BBB and triggers neuroinflammation, which may substantially increase the likelihood of emergence of HIV-associated depression." (PMID 40313235, 2025). "Anti-TNF agents, validated in IBD, are being investigated for treatment-resistant depression, with infliximab showing benefit in patients with elevated inflammatory markers." (PMID 41154835, 2025). "Numerous studies indicate that levels of inflammatory cytokines, including interleukin (IL)-1β, IL-6, tumor necrosis factor alpha (TNF-α), and C-reactive protein (CRP), are elevated in patients suffering from depression." (PMID 40565663, 2025). "The results also showed a positive correlation between the serum concentrations of TNF-α, IL-6, and hs-CRP with depression scores before and after intervention in both groups." (PMID 39997208, 2025). "In a rat model of FM induced by reserpine, treatment with honokiol reduced pain, depression and anxiety, increased SOD and IL-10 levels, and decreased MDA, TNF-α and prostaglandin E2 (PGE2) levels." (PMID 41470214, 2025). "In a murine LPS-induced depression model, the MAOI tranylcypromine was shown to reduce the expression of pro-inflammatory cytokines IL-1β, IL-6, and TNF-α." (PMID 40277932, 2025).
depression (continued). "However, studies in mice demonstrated that TNF-α secreted from hippocampal microglia induces working memory deficits by acute stress, whereas increased IL-6 was found in microglia from mice that had undergone repeated social defeat stress, as well as in patients with treatment-resistant depression." (PMID 40722844, 2025). "Other studies have shown significant associations between various serum biomarkers—IL-2, IL-6, IL-10, IL1-B, TNF-α, CRP, CRH, and cortisol—and pregnancy-specific anxiety and depression across all trimesters of gestation." (PMID 40565847, 2025). "Pro-inflammatory proteins identified include TNF-α, IL-6, IL-1β and C-reactive protein (CRP) which have been found to be increased in individuals with depression." (PMID 39867847, 2025). "The study by Fox and colleagues showed that the stress-induced suppression of TNF-α and TNFR1 predicts the severity of alcohol consumption after treatment only in patients with alcohol dependence and subclinical depression." (PMID 40870425, 2025). "These authors used the Hamilton Depression Rating Scale (HAMD) scores and found linear correlations between depression severity and TNFα concentration." (PMID 40352929, 2025). "Proinflammatory cytokines, including interleukin (IL)‐6 and tumor necrosis factor (TNF)‐α, demonstrated good performance in accurately predicting depression in these patients." (PMID 40387308, 2025). "Elevated inflammatory markers, such as C-reactive protein (CRP) and pro-inflammatory cytokines (e.g., IL-6 and tumor necrosis factor-alpha (TNF-α)), have been consistently observed in individuals with depression." (PMID 40303511, 2025). "Inflammatory markers such as IL-1β, IL-6, TNF-α, IL-18, and CRP are commonly observed in animal models of depression." (PMID 40277932, 2025). "We observed significantly elevated serum TNF-α, IL-4, and IFN-γ levels in adolescents with depression." (PMID 39980978, 2025). "Recent research has revealed a crucial role for pro-inflammatory cytokines, including interleukin (IL)-1β, IL-6, and tumor necrosis factor (TNF)-α, in stress-induced depression." (PMID 40612748, 2025). "In this model, compared to the control cells, the levels of 5‐HT and GABA were significantly lower, while TNF‐α, IL‐1β, and IL‐6 levels were markedly higher in the CORT‐induced depression cell model." (PMID 40491976, 2025). "Most of the research used outcome indicators such as depression and anxiety scales and CRP, IL-6, and TNF-α levels." (PMID 41010394, 2025). "The intervention significantly reduced proinflammatory mediators (TNF-α, IL-17, IL-23, MCP-1, IFN-γ, and IL-12) and improved depression, anxiety, resilience and well-being with sustained effect over a three-week follow-up." (PMID 40517143, 2025). "Multiple studies have shown elevated levels of pro-inflammatory cytokines such as interleukin (IL)-1β, IL-6, tumor necrosis factor-α (TNF-α), and C-reactive protein (CRP) in patients with depression, particularly in those with treatment-resistant depression." (PMID 41303496, 2025). "The increase in the levels of proinflammatory cytokines (IL-1β, IL-6, IL-12, TNF-α, and IFN-γ) is also influenced by several mental disorders, including depression." (PMID 40331982, 2025). "Many inflammatory markers, such as IL-6 and TNF-α, exhibited increased levels in the hippocampus and prefrontal cortex (PFC) in major models of depression, such as chronic social defeat stress, chronic restraint stress, and chronic unpredictable mild stress." (PMID 39273621, 2024). "TNFα, IL-10, and MCP-1 (CCL2), biomarkers of inflammation, are also increased in people with depression." (PMID 39337564, 2024). "This aligns with literature describing how HIV infection increases the release of tumor necrosis factor-α, IFN-γ, interleukin (IL)-1, and IL-6, resulting in reduced 5-hydroxytryptamine transmission and ultimately leading to depression in PWH." (PMID 39902245, 2024).
depression (continued). "For example, the release of cytokines such as IL-12p70, TNF-α, IL-1β, IL-8, IL-6, and interferon-γ (IFN-γ) leads to CSC, including cancer-related fatigue (CRF), sleep disturbances, pain, anxiety, and depression." (PMID 38745774, 2024). "The intervention of Astragalus polysaccharide (APS) significantly reduced the levels of hippocampal TNF-α, IL-1β, and IL-6 in rats with CUS-induced depression." (PMID 38389919, 2024). "The effectiveness of the treatment was evaluated by the Hamilton Depression Scale (HAMD-17), Self-Depression Scale (SDS), Modified Barthel Index Score (MBI), and the serum levels of IL-1β, IL-6, IL-10, TNF-α, and INF-γ." (PMID 38370556, 2024). "EE-mediated analgesic effects, reduction of depression-like phenotype, and memory deficits in the CCI mice were explained by involvement of neuronal PAS domain 4 protein and lowered levels of TNFα in the hippocampus." (PMID 38256537, 2024). "Acupuncture prevented CUMS-induced depression-like behaviors by reversing the hyper-activation of the HMGB1/TLR4 signaling pathway and by downregulating IL-1β, TNF-α, and IL-6 in the amygdala (AMY) and blood of rats." (PMID 38791125, 2024). "For example, researchers have indicated that peripheral blood interleukin-1β (IL-1β), IL-6, tumor necrosis factor-α (TNF-α), and C-reactive protein are the most reliable biomarkers of inflammation in patients with depression." (PMID 38745774, 2024). "In fact, inflammatory markers such as tumor necrosis factor-alpha and interleukins 6 and 8 have been found to be markedly elevated in both AIBD and major depression." (PMID 38524019, 2024). "Other biological mediators related to depression and body composition parameters such as insulin growth factor-1 (IGF-1), tumor necrosis factor alpha (TNF-α), interleukin-8 (IL-8), and matrix metalloproteinase-9 (MMP-9) were also determined." (PMID 38362105, 2024). "Studies have shown that FMT can significantly improve depression-related performance and the composition of the fecal microbiota after CUMS, reverse increases in serum IL-6 and TNF levels, decrease 5-HT levels, and decrease hippocampal GABA levels." (PMID 38576620, 2024). "Many phase 3 trials for biologic therapies including TNF inhibitors, IL23 inhibitors, and IL17 inhibitors have included secondary outcomes including symptoms of depression and anxiety apart from quality of life." (PMID 39534221, 2024). "Among the volatile metabolites, 142 showed promising potential in treating insomnia, anxiety, and depression, implicating various biological and signaling pathways, predominantly ALB and TNF targets." (PMID 38774207, 2024). "An increase in the inflammatory markers, like C-reactive protein (CRP), interleukin (IL)-6, and tumor necrosis factor alpha (TNF-α), is often observed in patients with depression compared with healthy individuals." (PMID 38957737, 2024). "For example, studies included in a meta-analysis found an association between increased levels of IL-1RA, IL-6, IL-10, IL-12, sIL-2R, sIL-6R, and TNF-α, and decreased levels of IFN-γ and IL-4, in adult patients with depression." (PMID 38474387, 2024). "Studies have demonstrated elevated levels of TNF-α in the serum of PSD patients, with a positive correlation to depression severity, highlighting its potential role in PSD's pathophysiology." (PMID 38377025, 2024). "Elevated levels of inflammatory markers, especially interleukins (IL-6, IL-1α) and tumor necrosis factor-alpha (TNF α), have been identified in patients with major depressive disorder compared to the findings in healthy controls." (PMID 39595067, 2024).
depression (continued). "Blood samples and depression scale scores from elderly patients with depression show that the levels of TNF-α and BDNF are negatively correlated, and the ratio of TNF-α to BDNF is consistent with the Montgomery-Asberg Depression Rating Scale (MADRS)." (PMID 38898454, 2024). "This often manifests as abnormal cytokine concentrations, such as elevated levels of interleukin-6 (IL-6) and tumor necrosis factor-α (TNF-α), in patients with depression." (PMID 39329797, 2024). "Pathological studies have observed increased expression of TNF-α, IL, IL-1β, IL-6, and C-X3-C modality chemokine receptor 1 (CX3CR1) in the brain of patients with depression." (PMID 39654612, 2024). "It is evidenced by the vulnerable but significant correlation between the onset and development of depression and elevated levels of inflammatory markers such as CRP, TNF-α, IL-6, and IL-1 (Hacimusalar and Eşel, 2017)." (PMID 38384936, 2024). "In clinical studies, elevated levels of interleukin-6 (IL-6), interleukin-1β (IL-1β), and tumor necrosis factor-alpha (TNF-α), which belong to pro-inflammatory cytokines, have been observed in patients suffering from depression." (PMID 38892598, 2024). "Studies report that the plasma levels of proinflammatory cytokines such as interleukin-1β (IL-1β), IL-6, IL-12, CC chemokine Ligand (CCL-2), Tumor Necrosis Factor (TNF)-α, prostaglandin E2 are increased in patients suffering from depression." (PMID 38473935, 2024). "Together, these findings suggest that chronic-stress-induced BBB breakdown allows for the diffusion of TNF-α into the HPC, leading to the development of depression." (PMID 38791125, 2024). "So the administration of asiaticoside to depression-like mice restored the composition of the gut microbiota, could improve intestinal permeability and blood-brain barrier integrity, then could decrease the levels of IL-6, TNF-α, CRH, and CORT and increase hippocampal BDNF levels." (PMID 39494347, 2024). "Elevated levels of pro-inflammatory cytokines such as interleukin-6 (IL-6), tumor necrosis factor-alpha (TNF-α), and interleukin-1 beta (IL-1β) are commonly observed in individuals with major depressive disorders and suicidal behavior." (PMID 39290301, 2024). "Upon the administration of an antidepressant, reduced symptoms of depression were accompanied by a reduction in both IDO and TNF-α levels in the frontal cortex." (PMID 39064698, 2024). "The primary outcomes of such intervention were chosen to be changes in circulating levels of TNF-alpha (given its links to the TLR-2 pathway) and changes in anxiety and depression scores." (PMID 39408292, 2024). "Several studies have shown that the activation of the kynurenine (KYN) pathway in patients with depression is secondary to increased levels of the inflammatory cytokines interleukin (IL)-6, interferon (IFN)-α and tumor necrosis factor (TNF)-α." (PMID 39654767, 2024). "For example, clinical depression is accompanied by increased levels of interleukin (IL)-1β, IL-6, IL-8, IL-17, IFN-γ, and TNF-α." (PMID 37509005, 2023). "Recently, it was discovered that after depression was induced, MCP-1, IL-1, IL-6, and TNF expression increased significantly." (PMID 36986674, 2023). "The clinical study was based on the outcomes to demonstrate the relationship between TRD and inflammation in human models of depression by measuring inflammatory biomarkers CRP, Interleukin-6 (IL-6) and TNF-α and stress markers (corticosterone)." (PMID 36648973, 2023). "They found increased depression in the CON group but decreased depression in both the MCT and HIT groups and decreased levels of the pro-inflammatory cytokine TNF-α in the MCT group." (PMID 37700748, 2023).